RBM3 (RNA binding motif protein 3)
Description:
Cold-inducible mRNA binding protein that enhances global protein synthesis at both physiological and mild hypothermic temperatures. Reduces the relative abundance of microRNAs, when overexpressed. Enhances phosphorylation of translation initiation factors and active polysome formation (By similarity).
Synonyms: RNPL; IS1-RNPL
Tractability: PROTAC: its protein half-life has been measured.
Gene: Protein-coding gene on chromosome X (48,574,056 to 48,581,162, forward strand). Ensembl gene ENSG00000102317.
Subcellular location: Nucleus; Cytoplasm; Cell projection, dendrite
Subcellular location (Human Protein Atlas): Nucleoplasm
Gene Ontology:
Molecular function: protein binding; RNA binding; ribosomal large subunit binding; nucleic acid binding
Biological process: mRNA splicing, via spliceosome; positive regulation of translation; regulation of translation; RNA processing
Cellular component: nucleoplasm; cytoplasm; dendrite; large ribosomal subunit; nucleus; spliceosomal complex
Homologues: Orthologues: chimpanzee RBM3 (100% identical), guinea pig RBM3 (95% identical), mouse Rbm3 (95% identical), pig RBM3 (93% identical). Paralogues in human: CIRBP (68% identical), RBMX (58% identical), RBMXL1 (57% identical), RBMXL2 (54% identical), RBMXL3 (45% identical), RBMY1F (45% identical), RBMY1J (45% identical), RBMY1A1 (45% identical), RBMY1B (45% identical), RBMY1D (44% identical), RBMY1E (44% identical), HNRNPA1 (40% identical), and 24 more.
Diseases named in the same sentence as RBM3 in open-access papers:
RBM3 is named in the same sentence as 111 diseases in open-access papers, as found by Europe PMC text mining. Sharing a sentence is not in itself a finding about the gene and the disease. The quoted sentences say what the papers report.
prostate carcinoma (22 papers, 2010 to 2025). A carcinoma that arises from epithelial cells of the prostate gland. "The only exceptions published to date include astrocytoma and radically operated prostate cancer, in which high RBM3 expression is associated with a higher grade." (PMID 28118608, 2017). "Another study indicates that RBM3 attenuates the stemness and tumorigenesis of prostate cancer cells by inhibiting CD44 variant splicing, although this finding is in contrast to findings in colorectal cancer." (PMID 27147467, 2016). "In prostate cancer cells, RBM3 represses the variant v8–v10 of CD44 mRNA to inhibit stemness and tumorigenesis but enhances the standard spliced CD44 transcript." (PMID 27147467, 2016). "Very similar to breast cancer and EOC, a high level of RBM3, as an independent biomarker in prostate cancer, predicts a low risk of disease progression and recurrence." (PMID 27147467, 2016). "A strong association has been found between RBM3 overexpression and early biochemical prostate cancer recurrence in a large series." (PMID 26577765, 2015). "Our results demonstrate that high nuclear expression of RBM3 in prostate cancer is associated with a prolonged time to disease progression and, thus, a potential biomarker of favourable prognosis." (PMID 21955582, 2011). "Recently, increased RBM3 nuclear expression was also linked to cisplatin sensitivity and to an improvement in the prognosis in epithelial ovarian cancers, as well as to a prolonged time to disease progression in prostate cancer." (PMID 26577765, 2015). "Paradoxically, although RBM3 supports cellular stress resistance and survival, elevated expression has been linked to favorable prognoses in certain cancer types, including breast cancer, bladder cancer, gastric and esophageal cancers, ovarian cancer, prostate cancer, and malignant melanoma." (PMID 40506997, 2025). "The prognostic impact of the loss of RBM3 expression is markedly pronounced in estrogen receptor (ER)-positive breast cancer compared with ER-negative tumors, whereas RBM3 overexpression is a good prognostic marker in prostate cancer, which is governed by androgen receptor (AR) signaling." (PMID 28118608, 2017). "This approach aligns with prior studies in other tumor types, such as breast and prostate cancers, which also focused on nuclear RBM3 expression." (PMID 40506997, 2025). "In line with this, overexpression of RBM3 leads to a high reduction of prostate cancer cells’ stemness capacity, thus suggesting a role for RBM3 as a stemness suppressor." (PMID 38966428, 2024). "At the molecular level, RBM3 acts indirectly by inhibiting Wnt/β-catenin pathway activation, which is required for bone metastasis of prostate cancer cells, thus enhancing cellular migration and invasion." (PMID 38966428, 2024). "They indicated that RBM3 hindered the occurrence of prostate cancer because the tumor formation rate of PC3 cells overexpressed with RBM3 in nude mice was significantly lower than that in the control group." (PMID 34804951, 2021). "For instance, RBM3 plays a cancer-promoting role in breast and colorectal cancer, while it inhibits tumorigenesis in prostate cancer." (PMID 34804951, 2021). "A possible link between RBM3 expression and DNA integrity and repair in ovarian cancer has been suggested, and RBM3 has also been demonstrated to attenuate stem cell like properties of prostate cancer cells." (PMID 29464064, 2018). "RBM3 has been shown to be high-expressed in poorly differentiated, more aggressive prostate cancer and an independent prognostic factor predicting early recurrence." (PMID 28118608, 2017). "In fact, experiments in colorectal cancers have shown that RBM3 regulates Wnt/β-catenin signaling to induce the stemness of cancer cells, in contrast to findings in prostate cancer cells." (PMID 27147467, 2016).
prostate carcinoma (continued). "RBM3 has been shown to be a prognostic biomarker in several cancers, e.g. urothelial cancer, breast cancer, colorectal cancer, prostate cancer, esophageal and gastric adenocarcinoma and ovarian cancer." (PMID 25811459, 2015). "Down-regulation of cold-inducible proteins including RBM3 in prostate cancer cells by exposure to hyperthermia enhanced cancer cell response to chemotherapy." (PMID 26577765, 2015). "Low nuclear expression of the RNA-binding motif protein 3 (RBM3) has previously been found to be associated with poor prognosis in several cancer forms e.g. breast, ovarian, colorectal, prostate cancer and malignant melanoma." (PMID 23565664, 2013). "We have previously demonstrated that high nuclear expression of the RNA binding motif protein 3 (RBM3) is associated with an improved outcome in several major cancer forms, i.e. breast, ovarian, colorectal and prostate cancer and malignant melanoma." (PMID 22805320, 2012). "In this study, we investigated the prognostic impact of RBM3 expression in prostate cancer by immunohistochemical (IHC) analysis of benign and malignant specimens from 88 patients treated with radical prostatectomy." (PMID 21955582, 2011). "The value of RBM3 for prognostication, treatment stratification and follow-up of prostate cancer patients should be further validated in larger studies." (PMID 21955582, 2011). "The aim of this study was to examine the prognostic impact of immunohistochemical RBM3 expression in prostate cancer." (PMID 21955582, 2011). "RBM3 has previously been explored as a prognostic biomarker in multiple malignancies, including breast cancer, bladder cancer, gastric and esophageal cancers, OC, prostate cancer, and malignant melanoma." (PMID 40506997, 2025). "Since RBM3 expression is suppressed in the bone microenvironment, a potential therapeutic strategy could involve restoring RBM3 expression to inhibit bone metastasis in prostate cancer." (PMID 39682684, 2024). "Moreover, in prostate cancer cells, heat treatment upregulated heat shock proteins and down-regulated cold shock proteins [i.e., Cirbp and RNA binding motif protein 3 (Rbm3)]." (PMID 38419081, 2024). "In conclusion, restoring the expression of RBM3, which results in suppression in the bone microenvironment, could be a possible beneficial therapeutic approach for inhibiting prostate cancer bone metastasis." (PMID 38966428, 2024). "Specifically, overexpression of RBM3 reduces the expression of CD44v8-v10 and promotes the splicing of CD44s, which is known to have an inhibitory effect on metastasis, thus reducing the stemness properties of prostate cancer cells (PC3 cells)." (PMID 39682684, 2024). "In prostate cancer, RBM3 has been shown to impact the alternative splicing of CD44." (PMID 39682684, 2024). "Interestingly, we found that high expression of RBM3 significantly affected the stem-like properties of prostate cancer cells." (PMID 37190171, 2023). "RBM3 attenuated prostate cancer stem cell-like properties and tumorigenic potential." (PMID 34804951, 2021). "Although RBM3 is overexpressed in prostate cancer, different prognostic results have been reported." (PMID 28118608, 2017). "At the same time, for other cancers, such as astrocytoma, testicular and prostate cancer, the different expression level of RBM3 can also give some useful information for aiding physicians in monitoring disease metastatic and stratifying patient for adequate adjuvant treatment." (PMID 28118608, 2017). "However, another study suggested that high RBM3 attenuated the stemness and tumorigenesis by inhibiting CD44 variant splicing in prostate cancer cells." (PMID 28118608, 2017). "Interestingly, high RBM3 expression is found in poorly differentiated prostate tumor, whereas experimental downregulation of RBM3 in prostate cancer cells attenuates cell survival and enhances chemosensitivity in vitro." (PMID 27147467, 2016).
prostate carcinoma (continued). "One study suggests that the activation of ERG and the depletion of PTEN may contribute to RBM3-mediated good prognosis in radically operated prostate cancer." (PMID 27147467, 2016). "In addition, an increased vulnerability of cells to chemotherapy was noted after down-regulation of RBM3 in prostate cancer." (PMID 26577765, 2015). "Furthermore, RBM3 was found to be up-regulated in poorly differentiated prostate cancers in comparison to normal prostatic glands, as well as in low-grade vs high-grade astrocytomas." (PMID 26577765, 2015). "Our results indicate that immunohistochemical assessment of RBM3 expression in formalin-fixed paraffin embedded tumour samples could be a useful tool for prognostication and treatment stratification of prostate cancer patients." (PMID 21955582, 2011). "In prostate cancer PC3 cells, overexpression of RBM3 protein resulted in decreased expression of CD44 isoform 3 (CD44v8-v10) and an increased expression of CD44 isoform 4 (CD44s)." (PMID 38106992, 2023). "Further, we found that RBM3 upregulated m6A methylation on CTNNB1 in a METTL3-dependent manner, resulting in decreased stability of CTNNB1 mRNA, thus affecting the adaptive survival of prostate cancer in the bone microenvironment." (PMID 37190171, 2023). "In earlier studies, using the same large prostate cancer cohort we had described other very strong and often independent prognostic features such as for example ß3-tubulin, CD57, DAXX, HOXB13, KPNA2, RBM3, mTOR, p62, and TYMS, that might also be worth testing in multiparametric prognostic kits." (PMID 28415558, 2017).
malignant melanoma (16 papers, 2010 to 2025). "High RBM3 expression has been associated with improved survival in a number of malignancies, e.g. breast cancer, malignant melanoma, uroepithelial cancer, ovarian cancer, colorectal cancer, gastroesophageal cancer, and testicular cancer." (PMID 28800641, 2017). "Loss of RBM3 expression is associated with clinically more aggressive tumors and is an independent factor of poor prognosis in malignant melanoma." (PMID 28118608, 2017). "RBM3 is expressed in malignant melanoma, and low expression of RBM3 is associated with tumor progression and poor prognosis." (PMID 27147467, 2016). "The aim of the present study was to examine the associations of MCM3 expression with clinical outcome and RBM3 expression in a prospective, population-based cohort of melanoma." (PMID 22805320, 2012). "In light of the observed inverse association between expression of MCM3 and RBM3 in primary melanoma, we also examined differences in survival according to combined categories of low and high MCM3 and RBM3 expression." (PMID 22805320, 2012). "High expression of the RNA-binding protein RBM3 has previously been found to be associated with good prognosis in breast cancer, ovarian cancer, malignant melanoma and colorectal cancer." (PMID 21955582, 2011). "Moreover, the inverse association and prognostic impact of MCM3 and RBM3 expression indicate a possible interaction of these proteins in melanoma progression, the functional basis for which merits further study." (PMID 22805320, 2012). "Moreover, we have demonstrated an inverse association between tumour-specific expression of MCM3 and the RBM3 protein, loss of which has previously been found to correlate with tumour progression and poor prognosis in melanoma." (PMID 22805320, 2012). "In addition, it is demonstrated that the investigative biomarker RBM3 is down-regulated in metastatic deposits, associated with favourable histopathological parameters in primary melanomas and an independent predictor of a prolonged overall survival." (PMID 21777469, 2011). "In urothelial bladder cancer (UBC), RBM3 expression is reduced in metastases compared with primary melanoma." (PMID 28118608, 2017). "In melanoma, down-regulated RBM3 was observed in metastases compared to primary melanoma, in line with previous in vitro data down-regulated RBM3 in metastatic compared to primary melanoma cells, the low RBM3 tumors correlated with increased aggressiveness." (PMID 28118608, 2017). "Similar to UBC, reduced RBM3 expression is also observed in metastases in malignant melanoma compared with primary melanoma." (PMID 28118608, 2017). "In contrast to our previous study on malignant melanoma, where RBM3 was found to be downregulated in metastases compared to primary tumours, RBM3 expression was similar in primary tumours and matched lymph node metastases." (PMID 24963396, 2014). "Previous studies, e.g. in malignant melanoma, have demonstrated that the correlation between reduced RBM3 expression and overall survival was more evident than the correlation to recurrent disease." (PMID 23565664, 2013). "Immunohistochemical MCM3 expression was examined in 224 incident cases of primary melanoma from the Malmö Diet and Cancer Study, previously analysed for RBM3 expression." (PMID 22805320, 2012). "Longitudinal analysis did not reveal an altered expression of MCM3 in metastatic compared to primary melanoma, in contrast to RBM3, that was found to be downregulated in metastatic melanoma in two independent studies, including the present cohort." (PMID 22805320, 2012). "In the present study, we investigated the prognostic impact of immunohistochemical (IHC) RBM3 expression in 215 incident malignant melanomas in the prospective, population-based cohort Malmö Diet and Cancer Study (MDCS)." (PMID 21777469, 2011).
malignant melanoma (continued). "We have demonstrated that the RNA- and DNA-binding protein RBM3 is an independent biomarker of a prolonged OS in patients with primary malignant melanoma and that RBM3 expression is lost during progression of the disease." (PMID 21777469, 2011). "In a translational context, these findings are quite in line with a previous study, where RBM3 was demonstrated to be one of five down-regulated genes in an in vitro model of melanoma progression." (PMID 21777469, 2011). "In this study, the prognostic value of immunohistochemical RBM3 expression was assessed in incident cases of malignant melanoma from a prospective population-based cohort study." (PMID 21777469, 2011). "Reduced expression of the RNA-binding motif protein 3 (RBM3) has previously been demonstrated to correlate with an impaired prognosis in several major human cancer forms i.e. breast, ovarian, prostate, colorectal cancer and malignant melanoma." (PMID 23565664, 2013). "In malignant melanoma, a significantly downregulated expression of RBM3 was observed in metastases compared to primary melanoma, which is in line with previous in vitro data demonstrating a significant downregulation of RBM3 expression in metastatic compared to primary melanoma cells." (PMID 22805320, 2012). "However, down-regulation of RBM3 at the gene expression level has been demonstrated in an in vitro model of melanoma progression." (PMID 21777469, 2011). "However, RBM3 has been identified as one of five down-regulated genes in an in vitro model of melanoma progression, implying a beneficial impact on prognosis also in this cancer form." (PMID 20727170, 2010). "Hence, in the predictive setting in melanoma patients, thorough sampling and immunohistochemical analysis of metastatic deposits would be required in order to identify a comparatively small number of patients with RBM3 positive metastases." (PMID 21777469, 2011). "However, in contrast to the situation in ovarian cancer, where RBM3 showed a consistent expression pattern in primary tumours and omental deposits, the data presented here, and previous in vitro data, show that RBM3 is down-regulated in the majority of metastatic melanomas." (PMID 21777469, 2011). "Moreover, as RBM3 has been demonstrated to be a good prognostic biomarker in several other cancer forms, e.g. breast cancer and ovarian cancer, its clinical utility in stratification of melanoma patients should be validated in future studies." (PMID 21777469, 2011). "Reduced expression of the RNA binding motif protein 3 (RBM3) has been shown to correlate with tumour progression and poor prognosis in melanoma and several other cancer forms." (PMID 22805320, 2012). "The RNA binding motif protein 3 (RBM3) has been identified as a promising prognostic and potentially treatment predictive biomarker in several major cancer forms e.g. breast, ovarian, prostate, bladder and colorectal cancer as well as malignant melanoma." (PMID 24963396, 2014). "The prognostic value of RBM3 expression has, to our knowledge, not yet been investigated in malignant melanoma." (PMID 21777469, 2011). "However, a decreased RBM3 expression in cancerous relative to non-cancerous tissue has been reported in colon cancer, malignant melanoma, and urothelial bladder cancer." (PMID 30419865, 2018). "RBM3 expression has previously been shown not to be prognostic in thin melanomas ≤ 1 mm." (PMID 22805320, 2012). "In the case of RBM3, previous findings indicate that its nuclear rather than cytoplasmic localization is the most relevant parameter for prognostication, which is also demonstrated here for melanoma." (PMID 21777469, 2011).